E2F7 (E2F transcription factor 7)
Description:
Atypical E2F transcription factor that participates in various processes such as angiogenesis, polyploidization of specialized cells and DNA damage response. Mainly acts as a transcription repressor that binds DNA independently of DP proteins and specifically recognizes the E2 recognition site 5'-TTTC[CG]CGC-3'. Directly represses transcription of classical E2F transcription factors such as E2F1. Acts as a regulator of S-phase by recognizing and binding the E2-related site 5'-TTCCCGCC-3' and mediating repression of G1/S-regulated genes. Plays a key role in polyploidization of cells in placenta and liver by regulating the endocycle, probably by repressing genes promoting cytokinesis and antagonizing action of classical E2F proteins (E2F1, E2F2 and/or E2F3). Required for placental development by promoting polyploidization of trophoblast giant cells. Acts as a promoter of sprouting angiogenesis, possibly by acting as a transcription activator: associates with HIF1A, recognizes and binds the VEGFA promoter, which is different from canonical E2 recognition site, and activates expression of the VEGFA gene. Acts as a negative regulator of keratinocyte differentiation.
Tractability: PROTAC: ubiquitination databases record sites on it. Other modalities: a drug acting on it is in phase 2 or 3 trials.
Safety:
Unwanted effects reported when the protein is acted on. In parentheses: how it was acted on, where the effect was seen, and who reports it.
lumbar bone loss (source: ClinPGx)
Gene: Protein-coding gene on chromosome 12 (77,021,246 to 77,065,572, reverse strand). Ensembl gene ENSG00000165891.
Subcellular location: Nucleus
Subcellular location (Human Protein Atlas): Nucleoplasm; Cytosol; Primary cilium; Primary cilium tip
Gene Ontology:
Molecular function: cis-regulatory region sequence-specific DNA binding; DNA-binding transcription factor activity; DNA-binding transcription repressor activity; identical protein binding; protein binding; sequence-specific double-stranded DNA binding; DNA-binding transcription factor activity, RNA polymerase II-specific; RNA polymerase II cis-regulatory region sequence-specific DNA binding; DNA binding; DNA-binding transcription repressor activity, RNA polymerase II-specific; RNA polymerase II transcription regulatory region sequence-specific DNA binding
Biological process: negative regulation of transcription by RNA polymerase II; positive regulation of transcription by RNA polymerase II; sprouting angiogenesis; chorionic trophoblast cell differentiation; hepatocyte differentiation; negative regulation of cytokinesis; negative regulation of G1/S transition of mitotic cell cycle; placenta development; positive regulation of DNA endoreduplication; regulation of transcription by RNA polymerase II; trophoblast giant cell differentiation; regulation of DNA-templated transcription
Cellular component: nucleoplasm; chromatin; RNA polymerase II transcription regulator complex; nucleus; transcription regulator complex
Genetic constraint (gnomAD): Loss-of-function variants: 36 observed, 81.99 expected, observed/expected ratio (o/e) 0.44, 90% interval 0.34 to 0.58. The upper end of that interval is the gene's LOEUF score, 0.58, which puts it in group 2 of 6, group 1 being the genes least tolerant of losing a copy. Missense variants: 908 observed, 1,076.6 expected, observed/expected ratio (o/e) 0.84, 90% interval 0.8 to 0.89. Synonymous variants: 387 observed, 410.4 expected, observed/expected ratio (o/e) 0.94, 90% interval 0.87 to 1.03.
Homologues: Orthologues: chimpanzee E2F7 (99% identical), macaque E2F7 (97% identical), rabbit E2F7 (84% identical), guinea pig E2F7 (82% identical), rat E2f7 (79% identical), mouse E2f7 (79% identical), dog E2F7 (79% identical), pig E2F7 (78% identical), tropical clawed frog e2f7 (47% identical), zebrafish e2f7 (34% identical), Caenorhabditis elegans efl-3 (15% identical). Paralogues in human: E2F8 (35% identical), E2F4 (11% identical), E2F2 (10% identical), E2F3 (10% identical), E2F1 (9% identical), E2F5 (9% identical), E2F6 (7% identical).
Diseases named in the same sentence as E2F7 in open-access papers:
E2F7 is named in the same sentence as 72 diseases in open-access papers, as found by Europe PMC text mining. Sharing a sentence is not in itself a finding about the gene and the disease. The quoted sentences say what the papers report.
breast carcinoma (26 papers, 2015 to 2025). "In breast-cancer patients treated with tamoxifen, the abundant apperence of E2F7 is associated with a high possibility of recurrence and poor prognosis." (PMID 34781924, 2021). "E2F7 overexpression has been linked to tamoxifen and anthracycline resistance in breast cancer and head and neck squamous cell carcinoma, respectively." (PMID 31238586, 2019). "Loss of E2F7 confers resistance to poly-ADP-ribose polymerase (PARP) inhibitors in BRCA2-deficient breast cancer cells." (PMID 31703415, 2019). "E2F7 was also associated with breast cancer, and increased expression of E2F7 was significantly correlated with worse prognosis in patients being treated with tamoxifen." (PMID 30487158, 2018). "Analysis of multiple independent datasets indicated that E2F7 is significantly associated with the prognosis of breast cancer patients receiving tamoxifen." (PMID 26397135, 2015). "Finally, using several publicly available datasets, we found that high E2F7 expression is associated with higher relapse rate and poor prognosis of breast cancer patients receiving tamoxifen treatment." (PMID 26397135, 2015). "Moreover, high expression of E2F7 is correlated with high risk of relapse and poor prognosis in breast cancer patients receiving tamoxifen treatment." (PMID 26397135, 2015). "In conclusion, high E2F7 expression is significantly correlated with relapse risk and relapse free survival in a large population and may serve as an independent prognostic factor in breast cancer patients receiving tamoxifen." (PMID 26397135, 2015). "Both miR-26a knockdown and E2F transcription factor 7 (E2F7) overexpression induced tamoxifen resistance in ERα+ breast cancer cells." (PMID 40190354, 2025). "In breast cancer cells, E2F7 competes with E2F1 for binding to the promoter of its target gene, deleted in lymphocytic leukemia 2 (DLEU2)." (PMID 39613162, 2024). "CircFKBP8 and E2F7 are notably upregulated, and miR-432-5p is downregulated in breast cancer and cells." (PMID 39192374, 2024). "E2F7, a member of EF transcription factors, was known as a transcriptional repressor that influences the prognosis in a lot of tumors, such as breast cancer, endometrial carcinoma, gallbladder cancer, and colon cancer." (PMID 33828913, 2021). "Ectopic E2F7 expression has been signified to inhibit the therapeutic effect of miR-26a in breast cancer cells." (PMID 33489876, 2020). "Resistance to tamoxifen was overcome with miR-26a overexpression and E2F7 silencing, which resulted in reduced breast cancer cell viability and G1 cell cycle arrest." (PMID 31590453, 2019). "miR-26a was downregulated in ER+ breast cancer tissues whereas transcription factor E2F7 was upregulated." (PMID 31590453, 2019). "Further, we identified that elevated E2F7 was responsible for transcriptional repression of miR-15a/16 cluster in tamoxifen-resistant breast cancer cells." (PMID 26397135, 2015). "Further analysis of its targets and upstream regulatory mechanism showed that highly expressed E2F7 represses miR-15a/16 expression, which then up-regulates Bcl-2 and Cyclin E1 to induce tamoxifen resistance of breast cancer cells." (PMID 26397135, 2015). "The expression and function of E2F7 in breast cancer patients especially the relationship with tamoxifen resistance has never been reported." (PMID 26397135, 2015). "CircFKBP8 regulates breast cancer progression through the miR-432-5p/E2F7 axis." (PMID 39192374, 2024). "Interestingly, it was also reported that E2F7 was a tumor-promoting factor in breast cancer, inducing cancer cell proliferation, invasion, and metastasis." (PMID 35201478, 2021). "Additionally, E2F7 inhibits miR-15a/16 expression in breast cancer cells and the inhibition of these miRNAs is closely associated with tamoxifen resistance." (PMID 34944633, 2021). "Silencing the feedback loop to enhance the expression of miR-26a and downregulation of E2F7 may promote tamoxifen sensitivity in breast cancer cells." (PMID 34944633, 2021).
breast carcinoma (continued). "E2F7 plays an indispensable role in a variety of tumors, such as gallbladder cancer, rectal adenocarcinoma, and breast cancer, indicating that E2F7 may be a potential prognostic marker." (PMID 33042838, 2020). "E2F7, detected in lung cancer, involved in several cancer studies, which might act as an independent prognostic factor for breast cancer, and Squamous Cell Carcinoma, and gliomas." (PMID 30813883, 2019). "In addition, increased expression of E2F7, which often correlated with higher relapse and poor prognosis in tamoxifen-treated breast cancer patients, was found to inhibit transcription of the miR-15a/16 cluster." (PMID 31590453, 2019). "E2F7 is a known cell cycle regulator that is associated with poor survival in squamous cancers, upregulates c-MYC in various cancer cell lines, and induces tamoxifen resistance in breast cancer." (PMID 30092011, 2018). "Silencing E2F7 re-sensitizes breast cancer cells to tamoxifen through up-regulation of miR-15a/16." (PMID 26397135, 2015). "We now found that E2F7 was responsible for the repression of miR-15a/16 cluster by competing with E2F1 for binding to the promoter of miR-15a/16 host gene DLEU2 in tamoxifen resistant breast cancer cells." (PMID 26397135, 2015). "To further validate the prognostic value of E2F7 expression in a large population of breast cancer patients receiving tamoxifen, we did a meta-analysis of all the publicly available datasets that have complete survival data and clearly indicated the use of tamoxifen." (PMID 26397135, 2015). "E2F7 may be a valuable prognostic marker and a therapeutic target of tamoxifen resistance in breast cancer." (PMID 26397135, 2015). "The result of fixed effect model (p < 0.0001, HR = 1.83, 95%CI: 1.38-2.45) and random effect model (p = 0.0008, HR = 1.87, 95% CI: 1.30-2.71) of meta-analysis all indicated a significant prognostic impact of the E2F7 expression in a total of 696 tamoxifen-treated breast cancer patients." (PMID 26397135, 2015). "High expression of E2F7 may be developed as an independent marker for poor prognosis in breast cancer patients receiving tamoxifen and targeting E2F7 could be an effective strategy to overcome tamoxifen resistance." (PMID 26397135, 2015). "Recent evidence shows that the enhanced expression of E2F transcription factor 7 (E2F7) and the inhibition of miR-26a in ER+ breast cancer confers resistance to tamoxifen, suggesting a feedback loop." (PMID 34944633, 2021). "However, the link between abnormal expression of E2F7 and breast cancer remain unclear." (PMID 26397135, 2015). "Together, these results suggest that E2F7 and E2F8 may act as critical upstream transcriptional regulators of ESPL1, potentially promoting its overexpression in aggressive subtypes of breast cancer." (PMID 41268575, 2025). "For example, human E2F7 promotes proliferation and inhibits differentiation of acute myeloid leukemia cells and E2F8 overexpression promotes proliferation and tumorigenicity in breast cancer cell lines." (PMID 36063055, 2022). "E2F7 and E2F8 have been reported to be involved in several malignancies such as pancreatic cancer, gallbladder cancer, colorectal cancer, cervical cancer, breast cancer and lung cancer." (PMID 34532281, 2021). "E2F7(transcription factor 7), targeted by MIR424, miR-3666 and miR-26a, is highly expressed in multiple tumors such as endometrial carcinoma, breast cancer, colorectal cancer and glioma, indicating that E2F7 might constitute a potential therapeutic target." (PMID 31141819, 2019). "The ability of E2F7 to influence protein synthesis appeared not to be cell-type-specific as similar results were observed in both U2OS (osteosarcoma) and MCF7 (breast cancer) human cancer cell lines." (PMID 29760477, 2018).
breast carcinoma (continued). "Compared to normal tissue controls, however, the relocation of E2F7, but not E2F1, from the nucleus to the cytoplasm is induced by the overexpressed XPO1, and is commonly observed in colorectal cancer, prostate cancer, breast cancer, and HNSCC." (PMID 35197448, 2022).
glioma (21 papers, 2016 to 2025). A benign or malignant brain and spinal cord tumor that arises from glial cells (astrocytes, oligodendrocytes, ependymal cells). "This specific DDX11-AS1/miR-1183/E2F7 axis defines a previously unrecognized regulatory pathway underlying glioma progression." (PMID 41050080, 2025). "Various previous studies have shown that E2F7 was associated with several tumours, such as gallbladder cancer, gliomas and squamous cell carcinoma." (PMID 30487158, 2018). "Clinically, E2F7 transcript levels exhibited inverse correlation with miR-1183 abundance in glioma specimens." (PMID 41050080, 2025). "In our study, we elucidated the cell-autonomous oncogenic role of the DDX11-AS1/miR-1183/E2F7 axis in promoting glioma proliferation and invasion." (PMID 41050080, 2025). "In conclusion, our findings illustrated that DDX11-AS1 promoted glioma progression, which was primarily dependent on the miR-1183/E2F7 axis." (PMID 41050080, 2025). "Mechanistically, DDX11-AS1 competitively binds with miR-1183, in turn, promoting the proliferative and migratory actions of glioma cells through inducing E2F7 expression." (PMID 41050080, 2025). "Critically, inhibition of miR-1183 rescued the suppressive effects of DDX11-AS1 knockdown on glioma tumorigenic phenotypes and restored E2F7 expression levels." (PMID 41050080, 2025). "This study demonstrates that lncRNA DDX11-AS1 promotes glioma progression by regulating the miR-1183/E2F7 axis, indicating a potential therapeutic target for glioma." (PMID 41050080, 2025). "The clinically relevant E2F transcription factor, E2F7, was overexpressed among high-grade glioma patients compared with low-grade gliomas or normal tissues." (PMID 38183103, 2024). "The qRT-PCR results showed that compared with HA1800, the mRNA expression levels of AQP7 in human glioma cell lines were generally decreased, while the mRNA expression levels of E2F7 were generally increased." (PMID 37091789, 2023). "We first examined the expression of E2F factors in glioma; the result showed that E2F7 was the most significantly highly expressed among the family members in the Oncomine database." (PMID 32814835, 2020). "The expression of E2F7 was further detected in fresh glioma tissues by IHC and qRT−PCR; we found that E2F7 was also abnormally amplified in fresh glioblastoma tissues." (PMID 32814835, 2020). "In the local cohort, glioma patients with high E2F7 expression survived for a shorter time than those with low E2F7 expression." (PMID 32814835, 2020). "E2F7, a member of the E2F family of transcription factors, is overexpressed in many cancers, which can induce cell proliferation in tumors such as glioma." (PMID 32039732, 2020). "To study the role of miR-129- and E2F7-induced autophagy on viability of glioma cells, we performed MTT assay by using 3-MA, Beclin-1 siRNA (sibeclin-1) or Atg5 siRNA (siAtg5) to block autophagic flux, respectively." (PMID 26824182, 2016). "In conclusion, these findings identify a new function for miR-129 as a potent inducer of autophagy through a novel Notch-1/E2F7/Beclin-1 axis in glioma." (PMID 26824182, 2016). "To further explore the effect of miR-129- and E2F7-induced autophagy on cell proliferation of glioma cells, we performed 5-ethynyl-20-deoxyuridine incorporation (EdU) assay and colony formation assay." (PMID 26824182, 2016). "Consistent with the result of miR-129 overexpression and Notch-1 inhibition, E2F7 also increased Beclin-1 protein levels and induced autophagy in U87 and U251 glioma cells." (PMID 26824182, 2016). "Specifically, E2F7 promotes tumorigenesis via EZH2-mediated PTEN/AKT/mTOR pathway in glioma." (PMID 41050080, 2025). "Furthermore, E2F7 overexpression largely rescued the miR-1183-mediated suppression of glioma cell proliferation." (PMID 41050080, 2025).